MED12 (mediator complex subunit 12)
Diseases named in the same sentence as MED12 in open-access papers (continued):
Sharing a sentence is not in itself a finding about the gene and the disease.
breast carcinoma (17 papers, 2012 to 2026). "Next, proliferation assays were performed on our MED12 knockdown cells to confirm that loss of MED12 enhances breast cancer oncogenesis." (PMID 38915457, 2024). "In summary, we found that loss of MED12 promotes GLI3-dependent SHH signaling in breast cancer cells which subsequently leads to enhanced cell proliferation and colony formation ability." (PMID 38915457, 2024). "Catenin alpha 1 (CTNNA1) and mediator complex subunit 12 (MED12) have been shown to associate with breast cancer." (PMID 38137912, 2023). "Somatic mutations in MED12 exon 2 splice sites have previously been identified in breast cancer and were shown to cause intron retention." (PMID 27602765, 2016). "Our results show that loss of MED12 leads to enhanced cellular proliferation and colony formation of breast cancer cells through a mechanism that involves activation of GLI3-dependent SHH signaling, a pathway that is central to breast development and homeostasis." (PMID 38915457, 2024). "Thus, we hypothesize that alterations in MED12 causes dysregulation of SHH signaling in breast cancer cells to subsequently promote oncogenesis." (PMID 38915457, 2024). "In a separate study, the same authors demonstrated that CARM1 methylates MED12 and that methylation of MED12 sensitizes breast cancer lines to chemotherapy." (PMID 41516402, 2026). "In contrast to NSCLC, the function of MED12 appears intact in small-cell lung cancer, but assumes a different role in mediating drug response in breast cancer." (PMID 40833497, 2025). "In our study, we focused our efforts on a specific subset of breast cancer that harbors genetic alterations in the Mediator subunit 12 (MED12)." (PMID 38915457, 2024). "To find a personalized treatment option for this subset of breast cancer, we employed a natural compound screening strategy which uncovered a total of ten compounds that selectively target MED12 knockdown breast cancer cells." (PMID 38915457, 2024). "Since targeted therapy is rapidly rising as a superior treatment option for cancer patients, we next set out to uncover a novel treatment strategy for MED12 downregulated breast cancer." (PMID 38915457, 2024). "Overall, our results show that solasonine and AB23A are promising targeted therapies for breast cancer cells with dysregulated GLI3-dependent SHH signaling such as is seen in MED12-altered cells." (PMID 38915457, 2024). "More recently, however, mediator subunit 12 (MED12) has been identified as an additional genetic alteration that presents itself in up to 33% of breast cancers." (PMID 38915457, 2024). "To study the role of MED12 in breast cancer, we first generated a stable MED12 knockdown MCF-7 cell line through lentiviral-mediated shRNA delivery." (PMID 38915457, 2024). "On the other hand, methylation of MED12 has been found to render breast cancer cells sensitive to chemotherapeutic agents, indicating that MED12 has cancer type-specific functions." (PMID 35326717, 2022). "Next, we performed a RIP-qPCR assay of human breast cancer MCF7 cells using an anti-MED12 antibody, because these lencRNAs are present in relatively high levels in human breast cancer cells." (PMID 36430260, 2022). "CARM1 works by arginine methylation of proteins, which can mediate BAF155 and MED12 methylation to affect breast cancer chemoresistance." (PMID 33495408, 2021). "The methylation of MED12, which sensitizes breast cancer cells to chemotherapy, was also detected in pancreatic cancer cells." (PMID 33344439, 2020). "Previous studies have emphasized the importance of CARM1 in resistance to chemotherapy through methylating RNA polymerase II mediator complex subunit 12 (MED12), resulting in highly aggressive breast cancer that insensitive to drugs." (PMID 32487779, 2020). "Additionally, MED12 methylation was associated with elevated levels of p21/WAF1, which is associated with a poor prognosis in breast cancer patients undergoing chemotherapy." (PMID 40833497, 2025).
breast carcinoma (continued). "In conclusion, our study has provided critical insights into the mechanistic basis behind MED12-altered breast cancer progression and, importantly, how this disease could potentially be combatted." (PMID 38915457, 2024). "Furthermore, we successfully found two natural compounds that can potentially combat MED12-altered breast cancer by targeting the GLI3-dependent SHH signaling pathway." (PMID 38915457, 2024). "Thus, our findings provide promising insight into a novel personalized treatment strategy for patients suffering from MED12-altered breast cancer." (PMID 38915457, 2024). "Though this indicates that MED12 likely plays an important role in breast cancer oncogenesis there currently is very limited knowledge on the mechanism of action behind MED12-mediated breast cancer." (PMID 38915457, 2024). "In order to determine whether cohesin and Mediator are both required for estrogen-regulated transcription, we performed siRNA-mediated knockdown studies of both SMC3 and MED12 in MCF7 breast cancer cells." (PMID 22913342, 2012). "For breast cancer patients, known oncogenes and tumor suppressor genes such as ESR1, KRAS, PIK3CA, PIK3R1, FAT1, and MED12 were consistently identified in both ctDNA and tumor WES across patients." (PMID 37878600, 2023). "Similar to its impact on BRCA-knockout cells, MED12 depletion promoted olaparib and cisplatin resistance in BRCA1-mutant MDA-MB-436 breast cancer cells and BRCA2-mutant PEO1 ovarian cancer cells." (PMID 34871431, 2021). "CARM1-mediated methylation of MED12 sensitizes breast cancer cells to 5-fluorouracil but not to RTK inhibitors, suggesting a unique mechanism of drug response modulation in breast cancer compared with NSCLC." (PMID 40833497, 2025). "Though prior reports have established links between SHH signaling and breast cancer development, no studies to date have reported the potential role of MED12 in this process." (PMID 38915457, 2024).
Opitz-Kaveggia syndrome (14 papers, 2012 to 2025). "Variants in the MED12 gene have been described as associated with X-linked disorders such as Opitz-Kaveggia Syndrome [OMIM #305450], Lujan-Fryns Syndrome [OMIM #309520], and Ohdo Syndrome, X-linked [OMIM #300895]." (PMID 35390071, 2022). "In humans, mutations in MED12 cause two, rare, intellectual disability syndromes called FG syndrome and Lujan-Fryns (LF) syndrome, while in-frame insertions and deletions in MED12 are associated with a 1.8-fold increased risk of schizophrenia." (PMID 29530929, 2018). "Variants in MED12 have been associated with ID syndromes with congenital abnormalities, including Opitz-Kaveggia syndrome (MIM 305,450), Lujan-Fryns syndrome (MIM 309,520) and X-linked Ohdo syndrome (MIM 300,896)." (PMID 29740699, 2018). "Germline MED12 mutations are responsible for at least two forms of X-linked mental retardation: Opitz-Kaveggia syndrome (FG syndrome [MIM 305450]) and Lujan-Fryns syndrome (MIM 309520)." (PMID 22428002, 2012). "Hemizygous MED12 variations are linked to several X-linked developmental syndromes, including Opitz-Kaveggia syndrome (FG syndrome) (MIM #305450), Lujan-Fryns syndrome (MIM #309520), and X-linked Ohdo syndrome (MIM #300895), alongside non-X-linked intellectual disability (ID) syndrome." (PMID 41465117, 2025). "MED12 deficiency is a rare condition which includes the phenotypes of FG syndrome type 1 (FGS1, MIM: #305450), Lujan syndrome (LS, MIM: #309520), X-linked Ohdo syndrome (XLOS, MIM: #300895), non-specific intellectual disability (NSID), and Hardikar syndrome (HS, MIM: #301068)." (PMID 37501721, 2023). "Furthermore, two variants were located on the X-chromosome: one in MED12 underlying FG-syndrome (OMIM #305,450), and a suspected de novo variant in HUWE1 in a female patient (OMIM #309,590)." (PMID 33710394, 2021). "Functionally this relation could be caused by the GLI3-MED12 interaction at the MBD: pathogenic DNA variants in MED12 can cause Opitz-Kaveggia syndrome, a syndrome in which presentation includes corpus callosum agenesis, broad halluces and thumbs." (PMID 32591344, 2021). "Several X-linked developmental syndromes are associated with hemizygous MED12 variants, including Opitz–Kaveggia syndrome (FG syndrome, MIM 305450), Lujan–Fryns syndrome (MIM 309520), and X-linked Ohdo syndrome (MIM 300895), as well as non-syndromic X-linked ID." (PMID 33925166, 2021). "However, due to some similarity to other syndromes with ID such as FG syndrome caused by MED12 mutation, 1p36 deletion syndrome or 22q11.2 deletion syndrome and proved variable clinical expression, the use of NGS is recommended for disease differential diagnosis." (PMID 33930262, 2021). "Missense variants in MED12 cause FG syndrome, Lujan-Fryns syndrome, and Ohdo syndrome, as well as non-syndromic intellectual disability (ID) in hemizygous males." (PMID 33925166, 2021). "However, both the p.Arg961Trp variant found in FG syndrome and the p.Asn1007Ser variant found in Lujan syndrome are involved in the silencing activity of REST, indicating that these variants in the LS domain affect the relay of signals through MED12." (PMID 33925166, 2021).
phyllodes tumor (11 papers, 2015 to 2025). A benign, borderline, or malignant fibroepithelial neoplasm arising from the breast and rarely the prostate gland. "Phyllodes tumors presented marked temporal heterogeneity of MED12 mutation status, as 50% (3/6) of primary and recurrent phyllodes tumor pairs with MED12 mutation presented different MED12 mutations between the primary and recurrent tumors." (PMID 27806318, 2016). "We show that MED12 mutations are associated with benign behavior of phyllodes tumors, as they are detected less frequently in malignant PTs (27.6%) compared to benign (58.3%) and borderline (63.3%) PTs, respectively (p = 0.0036)." (PMID 27806318, 2016). "This comprehensive analysis elucidates the genomic landscape of phyllodes tumors, highlights molecular markers corresponding to histologic grade, broadens the range of tumors with frequent MED12 mutations, and identifies IGF1R and EGFR as potential therapeutic targets in malignant phyllodes tumors." (PMID 39996866, 2025). "Interestingly,MED12 mutations have also been found in considerable percentages of other breast tumors of presumed stromal origin Phyllodes tumors and malignant Phyllodes tumors." (PMID 30647905, 2018).
Lujan-Fryns syndrome (10 papers, 2012 to 2025). "Male germline variants in MED12 are involved in the X-linked intellectual disability syndromes FG syndrome, Lujan-Fryns syndrome, and Ohdo syndrome, as well as in non-syndromic intellectual disability." (PMID 33925166, 2021). "Previous studies have shown that MED12 mutations in FG and Lujan syndromes disrupt a mediator‐imposed constraint on GLI3‐dependent SHH signaling." (PMID 30729724, 2019). "A single missense mutation in MED12‐LS domain, N1007S, has been identified in the original Lujan syndrome family." (PMID 30729724, 2019). "Mutations in the human MED12 gene result in X-linked mental retardation disorders, including Opitz-Karreggia syndrome and Lujan syndrome, and these mutations are also associated with schizophrenia." (PMID 23342055, 2013). "Pathogenic variants in the MED12 gene cause multiple X-linked recessive disorders including FG syndrome type 1 (FGS1, MIM: #305450), Lujan syndrome (LS, MIM: #309520), X-linked Ohdo syndrome (XLOS, MIM: #300895), and non-specific intellectual disability (NSID)." (PMID 37501721, 2023).
smooth muscle tumor (10 papers, 2012 to 2025). A benign or malignant myomatous neoplasm arising from smooth muscle. "Although molecular advances, such as the identification of MED12 gene mutations, have enhanced our understanding of smooth muscle tumors, many cases are still diagnosed based on histological evaluation." (PMID 40861708, 2025). "Deletions of the gene encoding mediator subcomplex 12 (MED12) in human smooth muscle tumors rank among the most frequent genomic alterations in human tumors at all." (PMID 23738817, 2013). "We propose here that MED12 alterations could be implicated in the development of smooth muscle tumor and that its expression could be inhibited in malignant tumors." (PMID 22768200, 2012). "The present study describes for the first time main characteristics of MED12 deletions occurring in smooth muscle tumors." (PMID 23738817, 2013). "In summary, a total of 70 smooth muscle tumors with MED12 deletions including 46 cases published previously as well as 24 own unpublished cases have been analyzed." (PMID 23738817, 2013). "In contrast, the lengths of the MED12 deletions observed in smooth muscle tumors clustered between 2 and 43 bp and thus in many cases the length of the deletions even exceeded the range as defined for germline microdeletions (≤ 20 bp)." (PMID 23738817, 2013). "A total of 70 smooth muscle tumors with MED12 deletions retrieved from the literature (46 cases), as well as from further unpublished own cases (24 cases) were analyzed." (PMID 23738817, 2013).
colon cancer (7 papers, 2011 to 2025). "Loss of MED12 promotes the transition of a mesenchymal phenotype, which is accompanied by chemotherapy resistance in colon cancer patients and resistance to the tyrosinase inhibitor gefitinib in lung cancer." (PMID 30631358, 2018). "Consistent with our results, MED12 loss could induce an EMT-like phenotype through activation of TGF-βR signaling pathway, which was associated with resistance to chemotherapy such as 5-FU and cisplatin in colon cancer patients." (PMID 38467827, 2024). "Interestingly, CDK8 stimulates expression of MMP-9 in human colon cancer cells via Wnt/β-catenin-driven transcription, while MED12 plays an important role in regulating and mediating the function of CDK8 kinase module, and the activation of CDK8 kinase also requires the participation of MED12." (PMID 35456498, 2022).
colorectal cancer (7 papers, 2012 to 2025). A primary or metastatic malignant neoplasm that affects the colon or rectum. "When MED12 is mutated or its expression is lost, it may induce an epithelial/mesenchymal-like phenotype and activation of the TGF receptor pathway that confer drug resistance in colorectal cancer models." (PMID 38329392, 2024). "Recent findings showed that MED12 (Mediator Complex Subunit 12) expression was able to modulate TGF-β signaling and to influence chemotherapeutic response in colorectal cancer cells." (PMID 26956045, 2016). "Moreover, 3/4 driver-downregulated genes showed at least weak evidence of TSG role in the matched tissue (MED12 in brain, SF3B4 in breast, and CBLB in colorectal cancer), with the remaining 1 gene being classified as CGC TSG (CLTC)." (PMID 36625266, 2023).
fibroepithelial tumors (7 papers, 2016 to 2025). "The MED12 gene is the most frequently mutated gene in fibroepithelial tumors, representing an early driver event in tumorigenesis." (PMID 41458625, 2025). "The high prevalence of MED12 mutations in fibroepithelial tumors suggests that it is a somatic driver gene for fibroepithelial tumorigenesis." (PMID 35071776, 2022). "The high prevalence of these MED12 mutations in fibroepithelial tumors suggests that MED12 is a critical driver gene in fibroepithelial tumorigenesis." (PMID 27806318, 2016). "Highly recurrent MED12 (Mediator complex subunit 12) somatic mutations have been identified in fibroepithelial tumors: in as many as 60% of breast FAs and 70% of breast PTs." (PMID 27806318, 2016). "In this context, a study described by Lerwill looks at the discovery of MED12 mutations in the pathogenesis of fibroepithelial tumors, along with other gene abnormalities in the progression pathway, which has allowed for the improvement of prognosis and diagnosis." (PMID 35885460, 2022). "The MED12 mutation is also known as a driver of tumorigenesis in fibroepithelial tumors." (PMID 32857809, 2020).
chronic lymphocytic leukemia (6 papers, 2015 to 2024). "MED12 mutations occur in uterine smooth muscle tumors, fibroepithelial tumors of the breast and in chronic lymphocytic leukemia." (PMID 30647905, 2018). "Apart from solid tumors,MED12 mutations recently were also detected in a significant percentage of roughly 5–9% of chronic lymphocytic leukemias (CLL) (Guièzeet al., 2015;Kämpjärviet al., 2015;Wuet al., 2017a)." (PMID 30647905, 2018). "Novel and potentially damaging variants in MED12 were observed in two cases and a MED12 exon 2 mutation (L36P), recently described in chronic lymphocytic leukemia, was seen in one case." (PMID 27203213, 2016). "MED12 mutations in the N-terminus were linked to NOTCH signaling activation in chronic lymphocytic leukemia, whilst the activation of NOTCH signaling is a promotor of disease progression and forms a supportive microenvironment in MM, therefore likely to play a role in its pathogenesis." (PMID 39769182, 2024).
Hardikar syndrome (5 papers, 2021 to 2025). "Thereafter, the Human Gene Mutation Database showed a case report linking Hardikar syndrome, a rare X‐linked dominant disorder caused by MED12 mutations, to a diaphragmatic hernia." (PMID 40078074, 2025). "The first is a missense variant in MED12 which in OMIM has disease assertions with four X-linked syndromic intellectual disability syndromes: Hardikar syndrome (MIM# 301068), Lujan–Fryns syndrome (MIM# 309520), Ohdo syndrome (MIM# 300895), and Opitz–Kaveggia syndrome (MIM# 305450)." (PMID 38674358, 2024). "Recently, female patients with de novo missense variants and de novo protein truncating variants in MED12 were described, resulting in a clinical spectrum centered around ID and Hardikar syndrome without ID." (PMID 33925166, 2021).
Intellectual disability (5 papers, 2015 to 2025). "Seven female individuals with multiple congenital anomalies, developmental delay and/or intellectual disability have been found to have a genetic variant of uncertain significance in the mediator complex subunit 12 gene (MED12 c.3412C>T, p.Arg1138Trp)." (PMID 41023835, 2025). "Up to date, two female carriers with the clinical symptoms and six MED12 variants, c.5898dupC, c.5922G > T, c.2312T > C, c.2545T > C, c.3443G > A, c.514G > C, have been reported with intellectual deficiency (ID) and clinical variability." (PMID 32174975, 2020). "Mutations in MED12 have also been associated with intellectual disability." (PMID 29740699, 2018). "For example, mutations in MED12 and MED23 in humans cause intellectual disabilities, and MED13L mutations cause congenital heart defects." (PMID 26445504, 2015). "FGS1 and LS are two allelic XLID syndromes, with mutations in the MED12 gene, that share some overlapping clinical features, such as dysgenesis of the corpus callosum, macrocephaly, hypotonia, intellectual disability, and behavioral disturbances." (PMID 32174975, 2020). "Additionally, particular MED12 variants do not always correspond to specific syndromes and are instead classified as MED12 non-specific intellectual disability." (PMID 41023835, 2025).